ALDH2 (aldehyde dehydrogenase 2 family member)
Diseases named in the same sentence as ALDH2 in open-access papers (continued):
Sharing a sentence is not in itself a finding about the gene and the disease.
esophageal cancer (continued). "However, ALDH2 deficiency markedly and dose-dependently increases the risk for esophageal cancer among alcohol consumers when compared with ALDH2-active subjects, which indicates that the esophageal mucosa contributes significantly to the exposure of the esophagus to carcinogenic ACH." (PMID 29303995, 2018). "ALDH2 polymorphism may be used to predict the survival, recurrence, and development of second-primary or other alcohol-related cancers for patients with alcohol-related cancers, particularly for esophageal cancer and head and neck cancer." (PMID 28253921, 2017). "In addition, the association between ALDH2*1/*2 and esophageal cancer became stronger with higher level of alcohol consumption (never drinker: OR = 1.21, 95% CI: 0.95–1.73; light drinker: OR = 3.79, 95% CI: 3.04–4.72; heavy drinker: OR = 6.50, 95% CI: 5.34–7.92)." (PMID 28253921, 2017). "For a Mendelian Randomization approach, genetic variants of ALDH2 with a strong influence on alcohol consumption might be more promising and have been successfully applied to study the impact of alcohol consumption on hypertension and esophageal cancer." (PMID 22363810, 2012). "Sensitivity analysis considering the ALDH2 genotype showed almost the same point estimate for all outcomes, except for esophageal cancer mortality." (PMID 40525786, 2025). "Even moderate alcohol consumption for ALDH2*2 carriers increases the odds ratio for developing aerodigestive track cancer (2.61, 1.19–5.75) and esophageal cancer (3.12, 1.95–5.01) due to acetaldehyde accumulation from inefficient acetaldehyde metabolism." (PMID 39075523, 2024). "Although the impact of ADH1B on esophageal cancer risk is well documented, this is the first identification of the genetic contribution of the other four (GCKR, KLB, ALDH1A1, and ALDH2) to esophageal cancer risk." (PMID 38277453, 2024). "We found that the C allele of ADH1B rs1229984 is an important risk factor for esophageal cancer, which was significantly promoted by the interaction of the ADH1B rs1229984 TC/CC genotype and ALDH2 rs671 GA/AA genotypes." (PMID 35670037, 2023). "The two genetic variants in the Chinese alcohol metabolizing‐related genes ALDH2 (rs671) and ADH1B (rs1229984 and rs2066702) that greatly alter alcohol metabolism and had a higher risk of acetaldehyde accumulation and esophageal cancer." (PMID 36655102, 2023). "This study focuses on analyzing associations between SNPs of essential enzymes for alcohol metabolism ADH1B, ADH1C, and ALDH2 and survival in esophageal cancer patients receiving postoperative radiotherapy." (PMID 36212135, 2022). "Looking at ADH1B * 1 / * 1 alone, the risk of esophageal cancer in drinkers was 2.71–3.22 times higher; however, the combination of ADH1B * 1 / * 1 and ALDH2 * 1 / * 2 had 12.45 times higher risk." (PMID 36028843, 2022). "The prognostic significance of ALDH1A1 in breast cancer, ALDH1 in rectal cancer, ALDH1 in esophageal cancer, and ALDH2 in oropharyngeal cancer has been explored by scholars." (PMID 34928471, 2022). "In studies involving East Asian populations, the presence of genetic polymorphisms in ADH1B (rs1229984) and ALDH2 (rs671), as well as alcohol consumption, individually or in combination, increase the risk of breast cancer, HNC, and esophageal cancer." (PMID 34680942, 2021). "We re-analyzed the data of ALDH2-alcohol interaction effect on esophageal cancer to reinterpret marginally significant ALDH2 and alcohol consumption on the basis of their synergistic effects." (PMID 30792419, 2019). "Alcohol, cigarette smoke, and alcohol metabolizing enzyme deficiencies such as aldehyde dehydrogenase-2 (ALDH2) are the main risk factors for HNC and esophageal cancer." (PMID 30606157, 2019).
esophageal cancer (continued). "Because of the high prevalence of ALDH2*2 allele among East Asian populations, East Asians may be more susceptible to the carcinogenic effect of alcohol, with most evidence coming from studies of esophageal cancer and head and neck cancer, while data for other cancers are more limited." (PMID 28253921, 2017). "Since drinkers with heterozygous ALDH2 are at high risk of HNSCC and esophageal cancer, as previous mentioned, we finally investigated the rates of second primary pharyngeal and esophageal cancers (SPPEC) for these patients according to ALDH2 genotype." (PMID 29206831, 2017). "In fact, certain studies have demonstrated a protective relationship of ALDH2 GA genotype with hepatic carcinoma and the ALDH2 AA genotype with esophageal cancer and liver cirrhosis." (PMID 24558407, 2014). "The alleles ALDH2 and MTHFR C677T were critical for determining individual susceptibility to esophageal cancer." (PMID 21672255, 2011). "Of interest, low frequencies of ALDH2*504Lys are also seen in Kazakhstan and Tajikistan, areas of moderate to high esophageal cancer incidence." (PMID 24281163, 2010). "The rs671 genotype stratification revealed that contributions to esophageal cancer risk from GCKR, ALDH1A1, and ALDH2 might be observable exclusively among heterozygotes." (PMID 38277453, 2024). "Furthermore, our preliminary data demonstrated a positive correlation between ALDH2 and IL-17A expression in certain cancers, such as head and neck carcinoma, colon adenocarcinoma, and esophageal cancer." (PMID 38226171, 2024). "The interaction analysis further highlighted the potential combined effect of GCKR, ADH1B, ALDH1A1, and ALDH2 with rs671 GA toward increased (GCKR, ADH1B, and ALDH1A1) or decreased (ALDH2) risk of esophageal cancer and thereby carries important implications for personalized prevention." (PMID 38277453, 2024). "Furthermore, other studies have also provided evidence of a synergistic effect of ALDH2 rs671 in esophageal cancer." (PMID 35670037, 2023). "Our data showed that participants carrying ADH1B rs1229984 TC/CC and ALDH2 rs671 GA/GG were at higher risk of esophagus cancer than noncarriers." (PMID 35670037, 2023). "In current drinkers, ALDH2 genotypes had a greater impact on esophageal cancer risk than in nondrinkers." (PMID 33750341, 2021). "Individuals with ALDH2*2,1 heterozygosity (40% of Asians) coding for an ALDH2 with less than 15% of activity, as compared to the normal ALDH mutation, have an increased risk of esophageal cancer when they consume alcohol chronically." (PMID 33669694, 2021). "Smoking history did not affect the association between ALDH2 polymorphisms and esophageal cancer in either sex." (PMID 33750341, 2021). "During subgroup analysis for nondrinkers, the ALDH2 GA/AA genotype revealed a higher risk of esophageal cancer than the ALDH2 GG genotype in women, unlike in men, presumably due to distinct hormonal receptors in both sexes." (PMID 33750341, 2021). "Considering that drinking is a major risk factor of esophageal cancer, regional distributions of DAF spectra of the ADH1B and ALDH2 functional alleles partly explain its similarity with those of drinking habit, and as a consequence, prevalence of esophageal cancer." (PMID 29691385, 2018). "Taking this risk into consideration, similar to published outlined measures for gastrointestinal cancers with reference to specific genetic variants, increased consideration should be given to developing screening measures for esophageal cancer in the ALDH2*2 population." (PMID 27835996, 2016). "As a precancerous disease of esophageal cancer, BE patients in Asian countries possessing a different phenotype of ALDH2 and ALDH3 and alcohol metabolism process may be more susceptible to alcohol than Western populations." (PMID 26542211, 2015). "The ALDH2*2 and MTHFR 677T alleles were associated with higher susceptibility to esophageal cancer." (PMID 21672255, 2011).
esophageal cancer (continued). "Notably, the ALDH2 genotype had a higher impact on the risk of esophageal cancer in current drinkers than that in nondrinkers." (PMID 33750341, 2021). "Furthermore, the relationship between ALDH2 polymorphisms and esophageal cancer has not been assessed in the South Korean population to date." (PMID 33750341, 2021). "Although the ALDH2 rs671 GA genotype has been associated with a high risk of esophageal cancer, this association could not be replicated by certain studies." (PMID 33750341, 2021). "Alarmingly, people with an ALDH2*2 variant and also an alcohol dehydrogenase variant (ADH1B, that causes a rapid conversion of alcohol to acetaldehyde) with a history of drinking alcohol and smoking cigarettes, have an odds ratio of 189 for developing esophageal cancer." (PMID 27835996, 2016). "Evidence suggests that drinkers with the ALDH2*2 have a higher incidence of HNSCC and esophageal cancer." (PMID 29206831, 2017). "Ratio of esophageal cancer was higher in ALDH2 rs671 GA genotype (0.45%, p = 0.005) than in the ALDH2 rs671 noncarriers." (PMID 35670037, 2023). "Several recent studies have shown that ALDH1A1, ALDH2 and ALDH3A1 may be related to different cancers, such as head and neck cancer (HNC), esophageal cancer, cholangiocarcinoma, and colorectal cancer (CRC)." (PMID 34680942, 2021). "We also observed that ALDH2 is expressed at high level by almost all seven analyzed cancer types except for skin cancer, whereas the expressions of ALDH3A1 and ALDH3A2 are higher in lung, pancreatic, and esophagus cancer." (PMID 30220009, 2019). "The ALDH2 locus, which is associated with aldehyde metabolism, hypertension and esophageal cancer, was positively selected in East Asians; HFST at ALDH2 was in the highest bin for the wider area (A1) but not so in the smaller areas." (PMID 29091727, 2017). "Therefore, the screening and health education of specific risk groups, including those with ALDH2 deficiency, atrophic gastritis, H. pylori infection, and regular users of PPI drugs, could have a major impact on the prevention of not only oral and esophageal cancers, but also gastric cancer." (PMID 25831092, 2015).
Hypertension (70 papers, 2012 to 2026). The presence of chronic increased pressure in the systemic arterial system. "Overweight, hypertension, dyslipidemia, ALDH2 rs671 G/A or A/A genotype were associated with coronary atherosclerosis in T2DM patients." (PMID 41948587, 2026). "Individuals with a history of smoking, alcohol consumption, or hypertension were more likely to carry the A allele, highlighting the influence of environmental factors on the prevalence of ALDH2 mutations." (PMID 40979589, 2025). "Our meta-analysis indicated that ALDH2 rs671 GG gene type was not only a risk factor for promoting the development of hypertension, but also in increasing BMI, blood pressure, FBG, TG, and LDL-C." (PMID 38567307, 2024). "Previous studies report that ALDH2 deficiency increases oxidative stress in the body and is a susceptibility factor for hypertension." (PMID 38783958, 2024). "Meanwhile, ALDH2 was also reported in previous GWAS to be associated with hypertension, triglyceride (TG) and body mass index (BMI)." (PMID 38567307, 2024). "In fact, in a recent clinical study, the ALDH2*2 mutant variant is associated with an increased risk of HFpEF in patients with hypertension, diabetes and coronary heart disease." (PMID 36142350, 2022). "ALDH2 rs671 G/A genotype and A allele were associated with a decreased risk of hypertension in drinkers, while drinkers carried A allele have lower SBP and TG level and higher HDL-C level." (PMID 35346052, 2022). "People who carried the ALDH2 rs671 A allele were less risk of developing hypertension, so ALDH2 rs671 A allele is protective factor for hypertension in Han Chinese." (PMID 35346052, 2022). "Study has shown that ALDH2 rs671 G/G genotype is a potent risk factor of hypertension among males in the general population in Japan." (PMID 35346052, 2022). "ALDH2 rs671 polymorphism has been proven to be closely related to the incidence of hypertension in the Asian population." (PMID 35409487, 2022). "Animal experiments have shown that decreased ALDH2 expression was associated with progression of hypertension." (PMID 35346052, 2022). "Studies have shown that ALDH2 is a protective factor against oxidative stress, ALDH2 deficiency increases oxidative stress which is the predisposing factor of hypertension." (PMID 35346052, 2022). "In the univariate analysis, ALDH2*2 (OR: 2.321; 95% CI, (1.160, 4.648); P = 0.017) and hypertension (OR: 1.953; 95% CI, (1.011, 3.772); P = 0.046) were risk factors of persistent AF." (PMID 36426220, 2022). "The ALDH2 G/A genotype in the co-dominant model (adjusted OR 1.251, 95% CI 1.024–1.528, P = 0.028) and ALDH2 A/A genotype in the recessive model (adjusted OR 1.221, 95% CI 1.008–1.478, P = 0.041) were significant risk factors for the presence of hypertension." (PMID 35346052, 2022). "Previous studies have confirmed that ALDH2 rs671 polymorphism is associated with body mass index (BMI), hypertension, and cancer, presumably due to the reduced capacity of inactivated ALDH2 to attenuate oxidative stress." (PMID 36292620, 2022). "Acetaldehyde dehydrogenase 2 (ALDH2) gene polymorphisms are associated with a high incidence of hypertension in Asian populations." (PMID 36229771, 2022). "On the other hand, ALDH2 deficiency exacerbated myocardial ischemia/reperfusion injury and hypertension-induced heart failure." (PMID 34203800, 2021). "The sex-stratified MAGMA analysis of hypertension and SBP indicate that ALDH2 is another possible variant having a significant effect on hypertension in the male population." (PMID 34828409, 2021). "Genetic association studies have recently shown that the ALDH2 rs671 polymorphism is a significant risk factor for hypertension, diabetes, and coronary heart diseases in Asian people." (PMID 33276716, 2020). "Although a number of studies have focused on the association between ALDH2 and single CRFs such as hypertension, diabetes, obesity, and dyslipidemia, and analyses, the association has not been clearly defined." (PMID 33276716, 2020).
Hypertension (continued). "Some studies have shown that the risk of systemic hypertension is up to twice as likely to occur in people with inactive or mutant ALDH2 alleles, which leads to variation in reactions to and unfavorable effects of alcohol." (PMID 32806703, 2020). "Individuals with the ALDH2 rs671 A allele have higher prevalence of hypertension, cardiovascular risk factors, and cerebral infarction." (PMID 32107439, 2020). "While confirming that alcohol intake was associated with an increased risk of hypertension, we demonstrated the possibility of using alcohol flushing as a marker of alcohol intake and as a valid proxy for the ALDH2 genetic variant in the Korean population." (PMID 29323248, 2018). "Pertaining to this study, several epidemiological studies indicated that ALDH2 is critical in cardiovascular disease: inactive ALDH2 genotype is associated with a higher incidence of myocardial infarction, angina and hypertension in humans." (PMID 29677191, 2018). "Heavy alcohol consumption conferred by ALDH2 genotype has been reported to be associated with hypertension in men." (PMID 29254215, 2017). "Based on these observations, it is plausible that the mutant ALDH2 serves as a beneficial factor against hypertension by altered drinking behavior and as an independent risk factor for hypertension." (PMID 29254215, 2017). "Heavy alcohol consumption also conferred by ALDH2 has been reported to be associated with hypertension in men." (PMID 29254215, 2017). "Recently, several studies confirmed that the ALDH2 rs671 polymorphism is associated with hypertension." (PMID 28894224, 2017). "In multivariate logistic regression analysis, the risk factors of essential hypertension in G genetype of ALDH2 rs671 were similar as in L genetype genetypes, However, the influence of lifestyle on hypertension were obviously different in the two groups." (PMID 28894224, 2017). "Hui24 obeserved that ALDH2 Glu/Glu genotype was the independent risk factor for the Japanese, especially in male patients with hypertension." (PMID 28894224, 2017). "Several studies have been conducted to examine the association between aldehyde dehydrogenase 2 family (ALDH2) rs671 polymorphism and essential hypertension (EH)." (PMID 28472173, 2017). "Further investigation on ALDH2 genotypes and the level of alcohol consumption suggests that the ALDH2∗1/∗1 genotype correlates with increased risk for hypertension among males primarily through its association with the level of alcohol consumption." (PMID 26491656, 2015). "We, however, have shown that alcohol consumption, even less than one drink/day, increases the risk of hypertension in Japanese individuals with the inactive ALDH2*2 allele." (PMID 24028448, 2013). "Three common tag single nucleotide polymorphisms (tagSNP) in the ALDH2 gene were genotyped in 1,134 subjects of Chinese origin from the Stanford Asia-Pacific Program for Hypertension and Insulin Resistance (SAPPHIRe) family cohort." (PMID 22839215, 2012). "We further explored the potential gene-environmental interaction between ALDH2 variants and environmental factors on hypertension risk." (PMID 22839215, 2012). "ALDH2 genetic variants were associated with progression to hypertension in a prospective Chinese cohort." (PMID 22839215, 2012). "Consistent with these experimental studies, several cross-sectional or case–control association studies have reported a significant association between ALDH2 SNPs and blood pressure or hypertension." (PMID 22839215, 2012). "Genetic variants near/within the ALDH2 gene encoding the mitochondrial aldehyde dehydrogenase 2 have been associated with blood pressure and hypertension in several case–control association studies in East Asian populations." (PMID 22839215, 2012). "Based on this observation, we propose that alcohol consumption level should be taken into account when ALDH2 genetic information is used to predict further hypertension risk." (PMID 22839215, 2012).